CYP2D7 (cytochrome P450 family 2 subfamily D member 7 (gene/pseudogene))
Description:
May be responsible for the metabolism of many drugs and environmental chemicals that it oxidizes. It may be involved in the metabolism of codeine to morphine. However, another study could not confirm it.
Synonyms: LOC105377203; formerly CYP2D; CYP2D@; CYP2D7P1; CYP2D7P
Target class: Enzyme; Oxidoreductase
Gene: Protein-coding gene on chromosome 22 (42,140,203 to 42,149,500, reverse strand). Ensembl gene ENSG00000205702.
Subcellular location: Membrane; Cytoplasm; Mitochondrion
Genetic constraint (gnomAD): Missense variants: 40 observed, 33.96 expected, observed/expected ratio (o/e) 1.18, 90% interval 0.91 to 1.53. Synonymous variants: 15 observed, 16.48 expected, observed/expected ratio (o/e) 0.91, 90% interval 0.61 to 1.4.
Diseases named in the same sentence as CYP2D7 in open-access papers:
CYP2D7 is named in the same sentence as 3 diseases in open-access papers, as found by Europe PMC text mining. Sharing a sentence is not in itself a finding about the gene and the disease. The quoted sentences say what the papers report.
G6PD deficiency (1 paper, 2018). An X-linked genetic condition caused by alterations in the gene G6PD that result in moderately to severely decreased activity levels of the enzyme glucose-6-phosphate dehydrogenase. "This study reports on the prevalence of G6PD deficiency as well as CYP2D6*4 and CYP2D7*17 mutations in a southern African malaria pre-elimination setting, with the aim of informing a low-dose PQ policy." (PMID 29558929, 2018).
CYP2D7 also shares sentences with these, for which no sentence is quoted: cancer (1 paper); malaria (1).